NNAT (neuronatin)
Description:
May participate in the maintenance of segment identity in the hindbrain and pituitary development, and maturation or maintenance of the overall structure of the nervous system. May function as a regulatory subunit of ion channels.
Synonyms: Peg5
Tractability: No criterion of Open Targets' tractability assessment is met for any kind of drug.
Gene: Protein-coding gene on chromosome 20 (37,521,206 to 37,523,690, forward strand). Ensembl gene ENSG00000053438.
Gene Ontology:
Biological process: brain development; positive regulation of insulin secretion; protein lipoylation
Cellular component: cytoplasm
Genetic constraint (gnomAD): Loss-of-function variants: 8 observed, 12.5 expected, observed/expected ratio (o/e) 0.64, 90% interval 0.38 to 1.15. The upper end of that interval is the gene's LOEUF score, 1.15, which puts it in group 5 of 6, group 1 being the genes least tolerant of losing a copy. Missense variants: 94 observed, 110.02 expected, observed/expected ratio (o/e) 0.85, 90% interval 0.72 to 1.01. Synonymous variants: 52 observed, 49.85 expected, observed/expected ratio (o/e) 1.04, 90% interval 0.83 to 1.31.
Homologues: Orthologues: chimpanzee NNAT (100% identical), macaque NNAT (100% identical), pig NNAT (99% identical), dog NNAT (65% identical).
Diseases named in the same sentence as NNAT in open-access papers:
NNAT is named in the same sentence as 49 diseases in open-access papers, as found by Europe PMC text mining. Sharing a sentence is not in itself a finding about the gene and the disease. The quoted sentences say what the papers report.
Obesity (16 papers, 2013 to 2025). Accumulation of substantial excess body fat. "Transcriptomic analysis further revealed upregulation of neuronatin, a protein previously linked to obesity and known to enhance SERCA2a-mediated Ca2+ uptake in neurons, pointing to a novel mechanism of SERCA2a dysregulation in the obese atrium." (PMID 40565066, 2025). "Transcriptomics showed that a high-fat diet upregulates neuronatin, a protein that has been implicated in obesity and is known to stimulate SERCA2a activity in neurons." (PMID 40565066, 2025). "Nnat encodes for neuronatin, a protein that plays a role in whole-body metabolic regulation and has been implicated in obesity." (PMID 40565066, 2025). "Human genetic studies have associated Neuronatin gene variants with anorexia nervosa (AN) and obesity." (PMID 37630847, 2023). "Neuronatin (Nnat) is an imprinted gene implicated in human obesity and widely expressed in neuroendocrine and metabolic tissues in a hormone- and nutrient-sensitive manner." (PMID 29864031, 2018). "Together, these findings suggest a role for neuronatin in the regulation of body weight and the pathophysiology of obesity, although the molecular mechanisms underlying these observations remain undetermined." (PMID 29864031, 2018). "Neuronatin expression is downregulated in obese children and has been associated with stochastic obesity in C57BL/6 mice." (PMID 30279096, 2018). "Neuronatin is emerging as a potentially interesting obesity gene, as mutations at the gene are associated with severe forms of obesity." (PMID 23482445, 2013). "Neuronatin is a novel proteolipid that is derived from an imprinted gene situated on the paternal allele; genetic variation at the neuronatin locus has been associated with obesity and variation in fat mass in humans." (PMID 23482445, 2013). "Genetic variation at the DNA locus encoding the novel proteolipid neuronatin has been associated with obesity, and we recently observed that neuronatin expression is reduced in subcutaneous adipose tissue from obese humans." (PMID 23482445, 2013). "Furthermore, loss of neuronatin subsequently affects feeding behavior and energy expenditure, and therefore susceptibility to obesity, in adulthood." (PMID 30279096, 2018). "In addition, an association between single nucleotide polymorphisms in the human neuronatin gene locus and severe obesity has been demonstrated in both children and adults." (PMID 23482445, 2013). "Obesity is associated with reduced neuronatin expression in humans." (PMID 23482445, 2013). "Therefore, though the exact role of NNAT in adipose tissue remains unclear, it is evident both in rodents and in humans that NNAT deletion and mutations are linked to obesity." (PMID 33089074, 2020). "In addition, the NNAT gene has been associated with severe obesity in childhood and adulthood." (PMID 29988473, 2018). "Transcriptomic analysis revealed that a high-fat diet upregulated neuronatin, a protein involved in obesity that enhances SERCA2-mediated Ca2+ reuptake in neurons." (PMID 40565066, 2025). "NNAT expression is diminished in rodent models of obesity and diabetes including the Zucker diabetic fatty (ZDF) rat model (85% decrease, p=0.0023, n=5) and obese ob/ob mice." (PMID 38512414, 2024). "We investigated the relationship between circulating Neuronatin, body mass index (BMI), body composition (BC), physical activity (PA), and psychometric outcomes in patients with AN, normal weight, and obesity." (PMID 37630847, 2023). "A total of 175 genes including thermogenic markers (UCP2, CKMT2, and CITED1) and 5 BATLAS markers (PPARGC1B, ACO2, ACSF2, NNAT, and DMRT2) were expressed less in active beige adipocytes carrying FTO obesity-risk variant as compared to risk-free carriers." (PMID 37416800, 2023). "The highest fold increase recorded in our dataset was 44.8 for NNAT gene (neuronatin; validated by RT-qPCR), which is highly expressed during oxidative stress and inflammation in response to dietary excess such as obesity." (PMID 34458349, 2021).
Obesity (continued). "Collectively, these data demonstrate the importance of the imprinted gene neuronatin in postnatal growth, adult energy homeostasis, and the pathogenesis of obesity." (PMID 30279096, 2018). "We recently showed that subcutaneous neuronatin expression declines with increasing obesity in humans, suggesting that the role of neuronatin in adipocytes merited more detailed investigation." (PMID 23482445, 2013). "The discovery that loss of neuronatin can promote UCP1 induction is a potentially important discovery, and more detailed analysis of neuronatin biochemistry is required before it can be proposed that manipulation of neuronatin represents a point for therapeutic intervention in human obesity." (PMID 23482445, 2013). "Neuronatin (NNAT) is a paternally expressed imprinted gene residing within a large intron of the bladder cancer associated protein (BLCAP) gene, variations in which are implicated in extremes of childhood and adult obesity." (PMID 23527188, 2013). "This implies that lower neuronatin expression, such as we observed in obese subjects, could contribute to obesity-induced alterations in glycogen and lipid metabolism." (PMID 23482445, 2013). "Lack of neuronatin also potentiated obesity caused by either aging or high fat diet feeding." (PMID 30279096, 2018). "Thus, it also appears logical that many pathways known to be modulated as a consequence of obesity may also impact on the expression of neuronatin." (PMID 23482445, 2013). "The molecular mechanisms involve the regulation of key metabolic pathways and genes, such as NNAT and SGK1, highlighting ISL’s potential as a therapeutic agent for obesity and related metabolic disorders." (PMID 40004080, 2025).
breast carcinoma (8 papers, 2013 to 2025). "Although the role of NNAT in Ca2+ homeostasis in breast cancer is unknown, several unrelated studies have collectively implicated elevated NNAT coincided with increased resting level of Ca2+, which was attributed to inhibition of SERCA2 activity." (PMID 37400769, 2023). "Furthermore, it has been found that increased NNAT expression levels are associated with poor prognosis in myxoid liposarcoma, lung cancer, and breast cancer." (PMID 36345357, 2022). "Collectively, these data, combined with our previous observations that elevated NNAT correlated with better survival of ER + breast cancer patients, suggest that NNAT is a key regulator of Ca2+ homeostasis that impacts ER + breast cancer cell progression." (PMID 37400769, 2023). "Compared with the empty vector controls, NNAT overexpression significantly elevated intracellular Ca2+ levels in both ER + breast cancer cell lines, which was reduced by blockade of ORAI channels but not TRPC channels." (PMID 37400769, 2023). "Collectively, our data suggest that NNAT expression is associated with ROS and PPAR signaling in ER + breast cancer patients from the TCGA cohort." (PMID 37400769, 2023). "It is possibly dominated by other downstream targets mediated by miR-708, for example, Rap1B and NNAT in ovarian and breast cancer." (PMID 37083947, 2023). "Overexpression of NNAT in ER + breast cancer cell lines suppresses proliferation and leads to elevated basal calcium levels and calcium release induced by thapsigargin, while NNAT CRISPRKO reduces intracellular calcium levels." (PMID 37400769, 2023). "Collectively, these data confirmed that NNAT is transcriptionally elevated in ER + breast cancer cells undergoing oxidative stress and peroxisome proliferation." (PMID 37400769, 2023). "Neuronatin (NNAT) was recently identified as a novel mediator of estrogen receptor-positive (ER+) breast cancer cell proliferation and migration, which correlated with decreased tumorigenic potential and prolonged patient survival." (PMID 37400769, 2023). "A recent study reported the involvement of NNAT with oxidative stress in ER + breast cancer." (PMID 39217334, 2024). "Confocal fluorescent microscopy revealed that NNAT co-localized to the EndoR and modulation of NNAT expression modify intracellular Ca2+ homeostasis in ER + breast cancer cells, fitting with reports that NNAT regulates intracellular Ca2+ in other physiological and pathophysiological settings." (PMID 37400769, 2023). "Elsewhere, NNAT has been reported to function as an intracellular Ca2+ regulator, leading to the hypothesis that NNAT suppresses ER + breast cancer by altering Ca2+ homeostasis in response to extracellular stimuli, such as ROS." (PMID 37400769, 2023). "Combined with the observations that NNAT colocalized to the EndoR and required the EndoR localization sequence for antiproliferative effects, the data collectively suggest that NNAT suppresses ER + breast cancer by altering EndoR Ca2+ storage." (PMID 37400769, 2023). "NNAT was localized in the endoplasmic reticulum and lysosomes of ER + breast cancer cells." (PMID 37400769, 2023). "ER + breast cancer patient RNAseq data from TCGA revealed an association of ROS and PPAR signaling with NNAT expression and in silico analysis of the NNAT promotor revealed consensus binding sites for NRF1 and PPARα/PPARγ, as well as the cell cycle transcription factor, E2F4." (PMID 37400769, 2023). "However, despite these observations, the molecular and pathophysiological role(s) of NNAT in ER + breast cancer remains unclear." (PMID 37400769, 2023). "Based on high protein homology with phospholamban, we hypothesized that NNAT mediates the homeostasis of intracellular calcium [Ca2+]i levels and endoplasmic reticulum (EndoR) function, which is frequently disrupted in ER + breast cancer and other malignancies." (PMID 37400769, 2023).
breast carcinoma (continued). "Exposure of ER + breast cancer cells to the ROS inducer, H2O2, or PPAR agonist, clofibrate, increased NNAT abundance, confirming that ROS and PPAR signaling activate NNAT expression." (PMID 37400769, 2023). "Briefly, the ER + breast cancer cell lines, T47D and ZR75, were co-transfected with the NNAT promoter-reporter construct, and plasmids that constitutively expressed E2F1, E2F4, NRF1, PPARα/RXR, PPARγ/RXR, or control (pLX304)." (PMID 37400769, 2023). "Based on the observation that NNAT expression correlated with oxidative stress pathways in ER + breast cancer patients, these data suggest that NNAT might mediate EndoR function(s) in the cellular response to ROS that impacts the progression of ER + breast cancer." (PMID 37400769, 2023). "Neuronatin (NNAT) is a small proteolipid (9kD) with high sequence homology to phospholamban, which was also recently identified as a novel modifier of estrogen receptor-positive (ER+) breast cancer incidence and survival." (PMID 37400769, 2023). "Collectively, the observations that NNAT is transcriptionally regulated by E2F4 and that overexpression of NNAT decreased ER + breast cancer cell proliferation suggest that cell cycle inhibition in response to ROS or PPAR signaling is potentially sensed and reinforced by NNAT." (PMID 37400769, 2023). "In addition, pharmacological inhibitors of key players in breast cancer cells Ca2+ signaling, ORAI and TRPC, were used to identify a potential Ca2+ pathway in which NNAT modulates Ca2+ levels." (PMID 37400769, 2023). "ORAI but not TRPC3 inhibition reduces NNAT-mediated elevation in intracellular Ca2+ concentration in breast cancer cells." (PMID 37400769, 2023). "Pharmacological inhibition of calcium channels revealed that NNAT regulates [Ca2+]i levels in breast cancer cells through the interaction with ORAI but not the TRPC signaling cascade." (PMID 37400769, 2023).
glioblastoma (5 papers, 2012 to 2020). The most malignant astrocytic tumor (WHO grade IV). "Xu and colleagues found that NNAT overexpression was associated with shortened survival in patients with glioblastoma multiforme." (PMID 32499872, 2020). "Aberrant transcriptional activity of NNAT has been reported in other tumors such as glioblastomas, neoplasms of eccrine, apocrine and sebaceous glands, malignant peripheral nerve sheath tumors, and others." (PMID 23825673, 2013).
pituitary adenoma (4 papers, 2012 to 2020). "Consistent with the results here, loss of expression of NNAT has been associated with promoter hypermethylation in pituitary adenoma." (PMID 23144859, 2012). "In addition to the present study focused on osteosarcoma, methylation-associated silencing of NNAT together with expression-associated suppression of neoplastic phenotypes such as colony formation, proliferation, or cell migration has been reported in liposarcoma and pituitary adenoma." (PMID 32499872, 2020). "Enforced expression of NNAT has been associated with decreased in vitro colony forming efficiency (CFE) and inhibition of proliferation in pituitary adenoma cells and decreased CFE in NSCLC, suggesting a potential tumor suppressor function in some cancers." (PMID 32499872, 2020). "NNAT was found to have low expression in normal brain, but was abundant within pituitary adenoma, a known positive control." (PMID 22624064, 2012). "mRNA expression of neuronatin (NNAT) has been reported in pituitary adenoma, prostatic cancer with neuroendocrine features, large cell neuroendocrine carcinoma lung and thyroid stimulating hormone-producing tumors in mice." (PMID 22937096, 2012).
prostate carcinoma (4 papers, 2012 to 2022). A carcinoma that arises from epithelial cells of the prostate gland. "Metformin promotes increased expression of miR-708-5p, leading to suppression of endoplasmic reticulum (ER) membrane protein neuronatin (NNAT) expression and subsequently induces apoptosis of prostate cancer cells through the ER stress pathway." (PMID 26075749, 2015). "Third, miR-708-5p exhibited an ER stress-dependent proapoptotic function mediated through NNAT in prostate cancer cells." (PMID 26075749, 2015). "Similar observations in prostate cancer cells transfected with NNAT siRNA further confirmed that metformin could lead to ER stress in prostate cancer cells through an miR-708-p/NNAT-regulated pathway." (PMID 26075749, 2015). "Besides its role in facilitating cancer cell metastasis, we explored and revealed a new function of NNAT in regulating apoptosis in prostate cancer cells." (PMID 26075749, 2015). "Downregulated NNAT, in turn, attenuates Ca2+ efflux from the ER to the cytoplasm and subsequently induces ER stress, as evidenced by ER stress markers and ribosome detachment, which eventually induces the apoptosis of prostate cancer cells." (PMID 26075749, 2015). "The anti-tumorigenic role of miR-708-5p in prostate cancer was not solely due to CD44, as miR-708-5p also targets RAC-beta serine/threonine-protein kinase (AKT2), NNAT, and karyopherin importin subunit alpha-4 (KPNA4) in prostate cancer." (PMID 29050362, 2017).
diabetes (3 papers, 2017 to 2024). "Changes in neuronatin might be a common downstream effect due to neuronal loss in multiple diseases such as Lafora disease, diabetes, and cancer." (PMID 35982059, 2022). "For the mechanisms of diabetes-induced β-cell injury, several studies have reported the roles of intracellular mediators such as neuronatin, dynamin-related protein-1, hydrogen-sulfide, c-Jun N-terminal kinase, and ubiquitin/proteasome system." (PMID 29057797, 2017).
Lafora disease (3 papers, 2020 to 2026). Lafora disease (LD) is a rare, inherited, severe, progressive myoclonic epilepsy characterized by myoclonus and/or generalized seizures, visual hallucinations (partial occipital seizures), and progressive neurological decline. "NNAT encodes neuronatin that stimulates glycogen synthesis by upregulating glycogen synthase and was previously found to be upregulated in Lafora disease." (PMID 31820119, 2020). "Indeed, neuronatin upregulation was shown to cause increased intracellular Ca2+ signaling, ER stress, proteasomal dysfunction and cell death in Lafora disease, and was shown to be a stress-responsive protein in the outer segment of retina photoreceptors." (PMID 31820119, 2020). "Neuronatin (NNAT) is small transmembrane protein involved in a wide range of physiological processes, such as white adipose tissue browning and neuronal plasticity, as well as pathological ones, such as Lafora disease caused by the formation of NNAT aggregates." (PMID 41955213, 2026).
medulloblastoma (3 papers, 2012 to 2020). A malignant, invasive embryonal neoplasm arising from the cerebellum. "Previous studies in medulloblastoma show that expression of both NNAT isoforms is associated with increased proliferation and anchorage independent growth, but that the presence of NNATα is the primary determinate of cytologic response." (PMID 22624064, 2012). "Similarly, overexpression of NNAT has been noted in medulloblastoma, and enforced NNAT expression, and particularly co-expression of both NNAT isoforms, in a medulloblastoma cell line resulted in increased clonogenicity in soft agar and in tumor xenograft formation." (PMID 32499872, 2020). "NNAT expression was found to be absent in the medulloblastoma cell line DAOY, as well as the two glioma derived cell lines." (PMID 22624064, 2012).
Angelman syndrome (2 papers, 2019 to 2023). A neurogenetic disorder characterized by severe intellectual deficit and distinct facial dysmorphic features. "Neuronatin (NNAT) is a developmentally regulated ER resident protein and negative regulator of SERCA that is expressed in the brain’s PVALB + GABAergic neurons; NNAT has also been implicated in abnormal neurodevelopment, including ASD and Angelman Syndrome (AS)." (PMID 36875674, 2023).
liposarcoma (2 papers, 2013 to 2020). A usually painless malignant tumor that arises from adipose tissue. "Since miR-708 is not differentially expressed in the liposarcoma samples of our collection, DNA methylation seems to be the predominant mechanism for the regulation of NNAT expression in liposarcomas." (PMID 24345474, 2013).
myxoid liposarcoma (2 papers, 2013 to 2022). A liposarcoma characterized by the presence of round non-lipogenic primitive mesenchymal cells and small signet ring lipoblasts within a myxoid stoma with a branching vascular pattern. "We propose novel biomarkers and genes relevant for pathogenesis, including NNAT as a potential tumor suppressor in myxoid liposarcomas." (PMID 24345474, 2013).